OXNAD1 (oxidoreductase NAD binding domain containing 1)
Synonyms: MGC15763; RFTN1-AS1
Tractability: Antibody: UniProt predicts a signal peptide or a membrane-spanning region. PROTAC: ubiquitination databases record sites on it; its protein half-life has been measured.
Gene: Protein-coding gene on chromosome 3 (16,265,160 to 16,350,299, forward strand). Ensembl gene ENSG00000154814.
Subcellular location (Human Protein Atlas): Nucleoplasm
Gene Ontology:
Molecular function: protein binding; oxidoreductase activity
Cellular component: mitochondrion
Genetic constraint (gnomAD): Loss-of-function variants: 31 observed, 29.5 expected, observed/expected ratio (o/e) 1.05, 90% interval 0.79 to 1.42. The upper end of that interval is the gene's LOEUF score, 1.42, which puts it in group 5 of 6, group 1 being the genes least tolerant of losing a copy. Missense variants: 395 observed, 385.31 expected, observed/expected ratio (o/e) 1.03, 90% interval 0.94 to 1.11. Synonymous variants: 132 observed, 139.77 expected, observed/expected ratio (o/e) 0.94, 90% interval 0.82 to 1.09.
Homologues: Orthologues: chimpanzee OXNAD1 (99% identical), macaque OXNAD1 (97% identical), guinea pig OXNAD1 (86% identical), pig OXNAD1 (86% identical), rabbit OXNAD1 (84% identical), rat Oxnad1 (81% identical), mouse Oxnad1 (80% identical), dog OXNAD1 (79% identical), tropical clawed frog oxnad1 (59% identical), zebrafish oxnad1 (49% identical). Paralogues in human: CYB5R4 (20% identical), CYB5R3 (18% identical), CYB5R1 (17% identical), CYB5RL (17% identical), CYB5R2 (16% identical).
Diseases named in the same sentence as OXNAD1 in open-access papers:
OXNAD1 is named in the same sentence as 7 diseases in open-access papers, as found by Europe PMC text mining. Sharing a sentence is not in itself a finding about the gene and the disease. The quoted sentences say what the papers report.
skin cancer (3 papers, 2015 to 2022). "PIK3IP1 was reported as a negative regulator for T-cell immunity, and OXNAD1 mutation was reported to be linked to skin cancer." (PMID 35865544, 2022). "Based on initial exome sequencing of 21 melanomas, we report frequent somatic mutations in skin cancers in a bidirectional promoter of diphthamide biosynthesis 3 (DPH3) and oxidoreductase NAD-binding domain containing 1 (OXNAD1) genes." (PMID 26416425, 2015). "The results from this study show occurrence of frequent somatic non-coding mutations adjacent to a pre-existing binding site for Ets transcription factors within the directional promoter of DPH3 and OXNAD1 genes in three major skin cancers." (PMID 26416425, 2015). "In this communication we report frequent somatic mutations within a bidirectional promoter region of DPH3 and OXNAD1 genes in three major types of skin cancers." (PMID 26416425, 2015).
lymphoma (1 paper, 2023). A malignant (clonal) proliferation of B- lymphocytes or T- lymphocytes which involves the lymph nodes, bone marrow and/or extranodal sites. "However, no information is available in relation to the potential role of the OXNAD1 gene in drug efficacy of lymphomas or other cancers." (PMID 37345090, 2023). "Among genes of which the SNPs were associated with the clinical outcomes of this cohort of patients, some have been previously related to cancer, including lymphomas (e.g., CDH3, OXNAD1)." (PMID 37345090, 2023).
OXNAD1 also shares sentences with these, for which no sentence is quoted: melanoma (2 papers); basal cell carcinoma (1); cancer (1); cardiovascular diseases (1); lung diseases (1).